COL3A1 (collagen type III alpha 1 chain)
Diseases named in the same sentence as COL3A1 in open-access papers (continued):
Sharing a sentence is not in itself a finding about the gene and the disease.
Stroke (8 papers, 2014 to 2024). Sudden impairment of blood flow to a part of the brain due to occlusion or rupture of an artery to the brain. "Our results suggest that the variant GG genotype of COL3A1/rs1800255 is associated with a severe course of AD, and as has been reported, the risk of stroke is significant in severe AD." (PMID 37109047, 2023). "Genetic analysis of three common variants in COL3A1 in a cohort of Chinese stroke patients suggested an association with stroke recurrence and prognosis." (PMID 34849481, 2021). "Polymorphism COL3A1/rs1800255 has been also linked with strokes in Chinese populations." (PMID 37109047, 2023). "Importantly, the relationship between COL3A1/rs1800255 polymorphism and stroke was examined in the Chinese population." (PMID 37109047, 2023). "An increased expression of the newly identified stroke genes Il6ra, Il6st, S100a4, Stat1, and Stat2, but also the known genes Col1a1, Col1a2, Col3a1, has been implicated in blood vessel remodeling and contributes to vascular rarefaction, leakage, and intracranial aneurysms." (PMID 24672479, 2014). "Thus, this polymorphism of COL3A1/rs1800255 may be a potential explanation for coexisting severe AD with stroke." (PMID 37109047, 2023). "The Col3a1 gene encodes the type III collagen α‐1 chain, and different variations in this gene affect the recurrence and prognosis of stroke and also play important roles in cortical development." (PMID 39295096, 2024). "Variations in genes related to vascular wall structure and function (such as COL3A1, EDN1) may influence stroke risk." (PMID 39655053, 2024). "A recent study which was consistent with our results, reported that the expression of col3a1 was reduced, and that of the E3 ubiquitin ligase atrogin-1 and muscle ring finger protein MuRF-1, which are known to regulate skeletal muscle and cardiac atrophy, was increased in stroke-induced mouse heart." (PMID 34481466, 2021). "Along this line of evidence, IL-18 after stroke is produced by microglia and contributes to fibrosis in the aged rat brain via STAT3 activation, leading to a large accumulation (237-fold over controls) of collagen III (Col3a1) transcripts that are normally expressed in adventitial fibroblasts." (PMID 24672479, 2014).
tendinopathy (8 papers, 2015 to 2023). "Using quantitative real-time PCR (qRT-PCR), the collagens Col1A1, Col3A1 and Col5A2 were found to be significantly upregulated in the tendinopathies and chronic ruptures compared to the intact control and the acute ruptured tendons." (PMID 29385715, 2018). "The results showed that tendinopathy tenocytes had higher levels of COL3A1, MMP1, COX2, SCX, ACTA2, and substance P gene expression compared to healthy tenocytes." (PMID 28598390, 2017). "In addition, a significant increase in the expression of Cox2, Mmp2, Mmp9, Col1a1, Col3a1, Vegf and Scx genes was also observed within the experimentally induced tendinopathy group compared with the control group." (PMID 33076550, 2020). "As shown in the results comparing the healthy and tendinopathy samples, the relative mRNA expressions of COL3A1, COX2, SCX, MMP1, and ACTA2 were increased by 1.4, 1.8, 2.7, 1.3, and 1.6 times in the SP-treated samples compared to the PBS-controls (p < 0.05 in all), respectively." (PMID 28598390, 2017). "In the moderate tendinopathy group, an increased COL1A1:COL3A1 ratio was found in PRP cultures and even moreso after LP-PRP injection." (PMID 36769065, 2023). "After SP treatment in our cultured healthy cells, levels of COL3A1, MMP1, and ACTA2 genes were increased, which were also shown in the tendinopathy samples." (PMID 28598390, 2017).
diabetes (7 papers, 2020 to 2024). "Still, two transcripts related to collagen synthesis (Col1a1 and Col3a1) were reduced in D3M rats compared to ND rats, suggesting that the advancement of diabetes weakens the structural strength and integrity of the colon." (PMID 34806320, 2021). "The UCD‐T2DM rat has a polygenic origin of diabetes and may be susceptible to fibrosis early in its lifespan; thus, the decrease Col1a1 and Col3a1 in an advanced state of diabetes could be a compensation mechanism for excess colonic fibrosis in this model." (PMID 34806320, 2021). "However, compared with nondiabetic mice subjected to renal IR, mice with early diabetes subjected to renal IR exhibited moderate Col1a1 and Col3a1 gene expression." (PMID 34561469, 2021).
nasopharyngeal carcinoma (7 papers, 2013 to 2022). A carcinoma arising from the nasopharyngeal epithelium. "Our present study showed that COL1A1 and COL3A1 were targeted by hsa-miR-29a/b/c that were decreased in radio-resistant nasopharyngeal carcinoma cells." (PMID 35274048, 2022). "For instance, miR-29a/b was reported to enhance cell migration and invasion in nasopharyngeal carcinoma progression by regulating SPARC and COL3A1 gene expression." (PMID 26336827, 2015). "miR-29 targeted several extracellular matrix genes including COL1A2, COL3A1 and COL5A2, and has been validated in nasopharyngeal carcinomas and HTM (human trabecular meshwork) cells." (PMID 24079748, 2013). "From these data we can assume that miR-29b has oncogenic activity by downregulating the tumour suppressor activity of PATZ1, in agreement with the ability of miR-29b to enhance cell migration and invasion in nasopharyngeal carcinoma progression by regulating SPARC and COL3A1 expression." (PMID 27125250, 2016).
osteosarcoma (7 papers, 2015 to 2026). A usually aggressive malignant bone-forming mesenchymal neoplasm, predominantly affecting adolescents and young adults. "In a similar way, upregulation of COL3A1 was observed in two MTX resistant osteosarcoma cell lines and correlated with miR-29a downregulation." (PMID 32283808, 2020). "In osteosarcoma, it was found that the microRNA-29 family may play a tumor inhibitory role in controlling methotrexate resistance and apoptosis by targeting COL3A1 or MCL1 apoptosis regulators." (PMID 35047627, 2021). "COL3A1, a subtype of Type III collagen, which is similar to Type I collagen, and primarily refers to the growth and metastasis of tumors such as osteosarcoma and nasopharyngeal tumors." (PMID 33543230, 2021).
renal cell carcinoma (7 papers, 2014 to 2023). "COL3A1 was reported to promote renal cell carcinoma growth and metastasis whereas COL4A1 facilitated hepatocellular carcinoma cells proliferation, migration and invasion by activating FAK-Src signaling." (PMID 36690975, 2023). "Furthermore, there was a significant correlation between COL3A1 and EMP1 in c9 fibroblasts, confirming the existence of COL3A1+/EMP1+ cells during the bone metastasis process in renal cell carcinoma." (PMID 38187400, 2023). "Interestingly, in renal cell carcinoma, let-7d miRNA suppresses growth, metastasis, and tumor macrophage infiltration by directly targeting COL3A1." (PMID 31687002, 2019).
aortic aneurysm (6 papers, 2017 to 2025). A ruptured aneurysm located in the wall of the proximal portion of the descending aorta proceeding from the arch of the aorta. "Genetic variants in COL3A1 are most associated with aortic aneurysms secondary to the disruption of collagen integrity in the adventitia and media of the aorta, as demonstrated by a murine model." (PMID 39996803, 2025). "Due to the similar architecture of the vessels, we hypothesize that COL3A1 mutations are associated with coronary artery aneurysmal disease, similar to their already-known role in the development of aortic aneurysmal disease." (PMID 39996803, 2025). "Interestingly, COL3A1 was reported to be one of etiologically linked genes in isolated vasculopathies such as aortic dissected aneurysm or CAD." (PMID 29050298, 2017). "The COL3A1 gene, encoding the pro-alpha chain of type III collagen, has been implicated in a range of collagen-mediated diseases such as Ehlers–Danlos syndrome and aortic aneurysms." (PMID 39996803, 2025).
lung carcinoma (6 papers, 2014 to 2024). "Furthermore, COL3A1 has been demonstrated to be a target of miR-29a/b, whose downregulation is responsible for the increased invasiveness of lung cancer." (PMID 31687002, 2019). "Interestingly, COL3A1 is the target of miR-29 family, and downregulation of this miRNA family is responsible for the increased invasiveness of lung cancer." (PMID 25193015, 2014). "COL3A1 could be an oncogene and promote drug resistance in lung cancer." (PMID 39497824, 2024). "COL3A1 is an integral ECM protein that is closely involved in malignant progression and drug resistance by regulating tumor immunity and EMT in a variety of cancers, particularly lung cancer." (PMID 37291533, 2023).
thoracic aortic aneurysm (6 papers, 2015 to 2026). An aneurysm formed in the wall of the proximal portion of the descending aorta proceeding from the arch of the aorta. "We analyzed nine genes associated with familial thoracic aortic aneurysms, the vascular Ehlers–Danlos gene COL3A1 and the MTHFR p.Ala222Val variant in 155 AAA patients." (PMID 26017485, 2015). "This is likely partially due to ascertainment bias, since the COL3A1 gene is present in the gene panel for thoracic aortic aneurysms and dissections and analyzed in all individuals with thoracic aortic aneurysms and dissections (n≥1000) who underwent genetic testing." (PMID 38623759, 2024). "One patient carried a CNV disrupting the COL3A1 and COL5A2 genes (vascular or hypermobility type of Ehlers–Danlos syndrome), and another patient a CNV in MYH11 (familial thoracic aortic aneurysms and dissections)." (PMID 35743335, 2022).
asthma (5 papers, 2017 to 2023). "In our study, we have investigated the association of SNPs in three collagen-coding genes, Col3A1/rs1800255, Col6A5/29rs12488457, and Col8A1/rs13081855, with the clinical manifestations of AD as well as the coexistence of asthma." (PMID 37109047, 2023). "COL3A1 expression was positively associated with ASM/Pi (R2 = 0.2089, p = 0.02) and Collagen/Pi (R2 = 0.2083, p = 0.03) in asthma." (PMID 29228930, 2017).
brain tumor (5 papers, 2016 to 2024). "Research has demonstrated that COL3A1 is selectively expressed by the microvasculature in brain tumors." (PMID 38962272, 2024). "A previous report indicates that COL3A1 gene had a prognostic implication in brain tumor." (PMID 26741506, 2016).
colitis (5 papers, 2019 to 2026). Inflammation of the colon. "Moreover, a slight decrease of colon mRNA expression of extracellular matrix-associated genes Fn1, Col1a1, Col3a1 and Tgf-β was observed in colitis mice receiving SuperMApo treatment." (PMID 35003066, 2021). "Also, Col1a1 and Col3a1 were overexpressed during active inflammation and murine colitis induced by 2,4,6-trinitrobenzene sulfonic acid (TNBS) hapten." (PMID 32478052, 2020). "In murine DSS-colitis, BMP9 attenuated disease severity, colon shortening, histopathological damage, inflammatory cytokines, and early pro-fibrotic markers (Col1a1, Col3a1, α-SMA)." (PMID 41751187, 2026).
colon cancer (5 papers, 2016 to 2023). "We also previously identified COL3A1 in the secretome of colon cancer-associated fibroblast (CAF)." (PMID 26741506, 2016). "COL3A1 could be a potential diagnostic biomarker of colon cancer." (PMID 26741506, 2016). "In colon cancer, the level of collagen expression is the key indicator to predicting the OS and risk, especially the types of COL1A1, COL1A2, COL3A1, COL4A3, and COL4A6." (PMID 36142424, 2022). "To address the protein expression of COL3A1 in colon cancers, we performed an IHC analysis of COL3A1 expression using a commercially available TMA containing 90 cases of colorectal adenocarcinoma, which 46 cases were completed and 44 were censored." (PMID 26741506, 2016). "We analyzed the differential expression of COL3A1 mRNA in colon cancer tissues and the normal counterparts using six microarray gene expression datasets deposited in Oncomine database (DB)." (PMID 26741506, 2016). "In this study, by analyzing Oncomine datasets, we found that COL3A1 expression was significantly upregulated in colon cancers (total 654 cases) comparing with normal controls (178 samples)." (PMID 26741506, 2016). "By using qRT-PCR, GUCA2A and COL3A1 were examined in colon cancer and rectal cancer." (PMID 37816854, 2023). "The results indicated that the overexpression of COL3A1 in colon cancers is common." (PMID 26741506, 2016). "Interestingly, in TCGA Colorectal dataset, COL3A1 was found to be significantly higher in all types of colon cancers including cecum, colon, rectal, and rectosigmoid cancer." (PMID 26741506, 2016). "Tissue staining of epithelial-specific COL3A1 expression had a superior prediction value of AUC 0.975 and the highest sensitivity/specificity of 95.2%/91.1%, which was comparable to spondin-2, another molecular marker of colon cancer." (PMID 26741506, 2016). "Furthermore, two m/z values (m/z 1303.6 (Col3A1) and m/z 1821.8) could be identified that show encouraging results for the identification of new prognostic biomarkers in colon cancer." (PMID 34771536, 2021).
head and neck squamous cell carcinoma (5 papers, 2021 to 2024). A squamous cell carcinoma that arises from any of the following anatomic sites: lip and oral cavity, nasal cavity, paranasal sinuses, pharynx, larynx, and salivary glands. "A study showed that patients with head and neck squamous cell carcinoma (HNSCC) with increased COL3A1 levels also had a higher level of resting CD4 + T cells and resting NK cells." (PMID 37415178, 2023). "Notably, a Krt15+/Col3a1+ cell type with epithelial‐mesenchymal features may play a crucial role in head and neck squamous cell carcinoma." (PMID 39245637, 2024).
hepatocellular carcinoma (5 papers, 2021 to 2025). A malignant tumor that arises from hepatocytes. "Moreover, in hepatocellular carcinoma, higher expression of COL3A1 has been implicated in tumor growth and angiogenesis, affecting patient prognosis." (PMID 38913913, 2024).
liver cancer (5 papers, 2012 to 2025). An epithelial or non-epithelial malignant neoplasm that arises from the liver. "We also find increased expression of myofibroblasts and fibrosis markers (PDGFRB, COL1A1, COL3A1, COL11A1) and early liver cancer markers (GPC3 and MUC1)." (PMID 41065540, 2025). "In addition, the hepatic stellate cells of liver cancer tissues had higher expression of activated markers including COL3A1 and ACTA2 than cells of noncancer tissues, which suggested the hepatic stellate cells of cancer tissues resembled aHSCs." (PMID 38036508, 2023).
Loeys-Dietz syndrome (5 papers, 2023 to 2025). Loeys-Dietz syndrome is a rare genetic connective tissue disorder characterized by a broad spectrum of craniofacial, vascular and skeletal manifestations with four genetic subtypes described forming a clinical continuum. "Importantly, the study confirmed the presence of COL3A1 variants in patients initially suspected of having other connective tissue disorders, such as Loeys-Dietz syndrome, emphasizing the clinical overlap between these conditions." (PMID 40740991, 2024).
Aortic dissection (4 papers, 2020 to 2024). Aortic dissection refers to a tear in the intimal layer of the aorta causing a separation between the intima and the medial layers of the aorta. "Aortic dissection was more frequent in individuals with a COL3A1 variant in the first quarter of the collagen helical domain (P=0.03)." (PMID 38623759, 2024). "We observed that vEDS individuals with aortic dissection mostly have a P/LP variant in the first quarter of the COL3A1 collagen helical domain, which is near the N terminus; thus, a shift in the collagen I/III ratio is expected to cause a more severe vascular phenotype." (PMID 38623759, 2024). "In patients in whom no mutations in FBN-1 and TGFβ were found, homozygous deletions in the COL3A1 gene have been identified, and these mutations lead to structural alterations of the collagen that could cause aortic dissection." (PMID 32273946, 2020).
atherosclerosis (4 papers, 2018 to 2025). A disease characterized by the build-up of fatty material and calcium deposition in the arterial wall resulting in partial or complete occlusion of the arterial lumen. "To validate sensitivity towards the known genes implicated in phenotypic switching of SMCs in atherosclerosis, we confirmed that markers of synthetic SMCs (Fn1, Col1a1, Col3a1, Col1a2, Eln, and Vcam1) were elevated in SMCTRAP-AS compared with SMCTRAP." (PMID 38289873, 2024). "The common mechanisms shared in both are linked with atherosclerosis signaling and inflammatory response with at least the following target genes: Tnfrsf12a, Pla2g2f, Il1f9, Col1a1, Col1a2, and Col3a1 in brain, while Tnfrsf12a, SELP, SELE, IL6, and IL1A in myocardium." (PMID 29681850, 2018). "As expected, all markers of ECM degeneration—Ki-67, Col3a1, and Mmp-9—had the highest expression in mice with advanced atherosclerosis (33-week-old group)." (PMID 40278373, 2025). "Using this method, we identified several hepatic regulators related to lipid metabolism (SC5D, LCAT and HMGCR), inflammation (IL1A) and fibrosis (PDGF and COL3A1) that were linked to a set of aorta target genes related to vascular inflammation (TNFA) and atherosclerosis signaling (CCL2 and FDFT1)." (PMID 35897797, 2022). "Gene regulatory network analysis identified specific liver regulators related to lipid metabolism (SC5D, LCAT and HMGCR), inflammation (IL1A) and fibrosis (PDGF, COL3A1), linked to a set of aorta target genes related to vascular inflammation (TNFA) and atherosclerosis signaling (CCL2 and FDFT1)." (PMID 35897797, 2022). "Ten key regulated genes (including Pla2g2f, Il1f9, Col1a1, Col1a2, and Col3a1 in the brain, while SELP, SELE, IL6, and IL1A in the myocardium, and Tnfrsf12a in both) are correlative with atherosclerosis signaling and inflammatory response." (PMID 29681850, 2018).
esophageal cancer (4 papers, 2022 to 2025). A primary or metastatic malignant neoplasm involving the esophagus. "Our study identified COL3A1, PLAU, and SPP1 as key ECM-associated genes with potential as early diagnostic biomarkers for esophageal cancer." (PMID 41465316, 2025). "In Esophageal Cancer COL3A1 is overexpressed with POSTN which further emphasizes the joint role they could have with CTHRC1." (PMID 36190948, 2022). "We identified COL3A1, PLAU, and SPP1 as early-stage esophageal cancer markers, highlighting the role of these genes in disease progression." (PMID 41465316, 2025). "The expression levels of COL3A1, PLAU, and SPP1 were significantly higher in esophageal cancer patients compared to healthy controls (p < 0.05 for all three genes)." (PMID 41465316, 2025). "Together, these mechanisms suggest that COL3A1, PLAU, and SPP1 not only serve as promising biomarkers for early-stage esophageal cancer but also contribute to the pathophysiology of the disease by facilitating key processes such as migration, invasion, and proliferation." (PMID 41465316, 2025).